COL4A4 (collagen type IV alpha 4 chain)
Diseases named in the same sentence as COL4A4 in open-access papers (continued):
Sharing a sentence is not in itself a finding about the gene and the disease.
Alport syndrome (continued). "The other cases result from mutations in the COL4A3 or COL4A4 genes, which cause autosomal recessive Alport syndrome (ARAS) and autosomal dominant Alport syndrome (ADAS)." (PMID 40406358, 2025). "As a result, the diagnosis of Autosomal Dominant Alport Syndrome (ADAS) was made for the patient, attributed to the COL4A4 (c.817-1 G > A) mutation." (PMID 40406358, 2025). "Alport syndrome is caused by variants in COL4A3, COL4A4, or COL4A5, which encode the α3α4α5 chains of type IV collagen." (PMID 41417821, 2025). "Autosomal recessive Alport syndrome (ARAS) is the second most prevalent type, resulting from pathogenic variants in both copies of either the COL4A3 or COL4A4 genes on chromosome 2." (PMID 40790091, 2025). "Alport syndrome (AS) is a hereditary glomerulopathy caused by mutations in the COL4A3, COL4A4, or COL4A5 genes, leading to progressive kidney decline and extrarenal manifestations." (PMID 41243004, 2025). "Alport syndrome is caused by pathogenic variants in COL4A3, COL4A4, and COL4A5 genes encoding the α3, α4, and α5 chains of collagen type IV, respectively." (PMID 40392259, 2025). "Alport syndrome (AS) is a hereditary glomerular disease caused by mutations in the COL4A3, COL4A4, and COL4A5 genes." (PMID 40406358, 2025). "Autosomal recessive Alport syndrome caused by disease-causing variants in COL4A3 and COL4A4 had a combined lifetime risk of 2.15 (1.64–2.79; European gnomAD), and 2.65 (2.24–3.12; worldwide gnomAD) per 100,000." (PMID 40677321, 2025). "Genetically, Alport syndrome is caused by pathogenic variants in type IV collagen genes (COL4A3, COL4A4, and COL4A5), which lead to abnormalities in the glomerular basement membrane resulting in kidney dysfunction and progressive renal failure." (PMID 40852417, 2025). "The most common form of digenic Alport syndrome involves pathogenic variants in both COL4A3 and COL4A4 genes, potentially resulting in a more severe clinical phenotype compared to individuals with a single variant." (PMID 40004525, 2025). "Specific Alport syndrome pathogenic variants in COL4A3 and COL4A4 can cause sub-clinical phenotypes in some patients, and severe manifestations of disease in others." (PMID 39883360, 2025). "A recent publication identified 12 genes, including the three genes associated with Alport syndrome (COL4A3, COL4A4, COL4A5), on a 274‐gene panel with the potential for carrier manifestations during pregnancy." (PMID 40317772, 2025). "Alport syndrome (AS) is a hereditary kidney disorder caused by mutations in COL4A3, COL4A4, and COL4A5, which often lead to progressive renal failure." (PMID 41290692, 2025). "The X-linked form of Alport syndrome is caused by variants in the COL4A5 gene, and the autosomal form is caused by variants in COL4A3 or COL4A4." (PMID 40392259, 2025). "We aimed to determine the frequency of variants in the Alport syndrome genes (COL4A3, COL4A4 or COL4A5) in individuals under 18 years of age presenting with persistent microscopic haematuria to a single specialist centre in the UK over a 10-year period." (PMID 39349776, 2025). "The majority (57%) were located in the COL4A5 gene, reflecting the predominance of X-linked inheritance in Alport syndrome, while variants in the COL4A3 (19%) and COL4A4 (24%) genes accounted for autosomal forms of the disease." (PMID 40004525, 2025). "A well-described hereditary GBM disease is Alport syndrome, which is associated with a progressive glomerular disease, hearing loss, and lens defects due to genetic variants in the genes COL4A3, COL4A4, or COL4A5." (PMID 41299396, 2025). "The rarest form is autosomal dominant Alport syndrome (ADAS), which accounts for about 5% of cases and can be caused by a single inherited copy of a mutated COL4A3 or COL4A4 gene." (PMID 40790091, 2025). "Alport syndrome involves chronic progressive kidney failure and extrarenal organ damage caused by COL4A3, COL4A4, and COL4A5 mutations." (PMID 39924725, 2025).
Alport syndrome (continued). "The syndrome is caused by mutations in type IV collagen genes (COL4A3, COL4A4, or COL4A5), with X-linked Alport syndrome (XLAS) accounting for approximately 80% of cases." (PMID 40852417, 2025). "In Alport syndrome, disruption of the GBM caused by variants in COL4A3, COL4A4, or COL4A5 causes podocyte dysfunction and proteinuria, proliferation of Bowman’s epithelial cells, and progressive glomerulosclerosis." (PMID 40527586, 2025). "Alport syndrome (AS) is a genetically heterogeneous disorder resulting from mutations in the collagen IV genes COL4A3, COL4A4, and COL4A5." (PMID 38433557, 2024). "Alport Syndrome (AS) is the most common genetic glomerular disease, and it is caused by COL4A3, COL4A4, and COL4A5 pathogenic variants." (PMID 38790225, 2024). "People with one altered and one normal copy of an autosomal COL4A3 or COL4A4 gene have autosomal dominant (AD) Alport syndrome." (PMID 38745975, 2024). "For the other forms of Alport syndrome, where variants are found in the COL4A3 or COL4A4 genes, there are different patterns of inheritance:1." (PMID 38745975, 2024). "Alport syndrome (AS), a hereditary kidney disease with a high risk for renal failure, is attributed to pathogenic variants in genes COL4A3, COL4A4, and COL4A5 that encode type IV collagen." (PMID 39071776, 2024). "Alport syndrome occurs at a prevalence of ~ 1% through mutations in COL4A3 (2q36.3), COL4A4 (2q36.3) or COL4A5 (Xq22.3)." (PMID 38668984, 2024). "Mono-allelic variants in COL4A3 and COL4A4 (COL4A3/COL4A4) have been identified in a spectrum of glomerular basement membrane nephropathies, including thin basement membrane nephropathy and autosomal dominant Alport syndrome." (PMID 36925663, 2023). "A pathogenic variant in COL4A5 confirms the diagnosis of X-linked Alport syndrome, whereas variants in COL4A3 or COL4A4 confirm the diagnosis of Autosomal Dominant or Autosomal Recessive Alport Syndrome." (PMID 37895203, 2023). "Pathogenic variants in COL4A5 are responsible for the severe X-linked glomerulopathy, Alport syndrome (AS), while homozygous or compound heterozygous variants in the COL4A3 or the COL4A4 gene cause autosomal recessive AS." (PMID 37761826, 2023). "Alport syndrome (AS) is the most common inherited glomerular disease caused by pathogenic variants of the COL4A3, COL4A4, or COL4A5 genes that encode type IV collagens." (PMID 36968823, 2023). "Alport syndrome (AS) is caused by mutations in COL4A3, COL4A4 or COL4A5 genes, mainly pathophysicalological alterations affect the kidney, but the pathophysiology of AS is still not fully understood." (PMID 36968823, 2023). "Alport syndrome (AS) is a rare disease characterized by defective glomerular basement membranes, caused by mutations in COL4A3, COL4A4, and COL4A5, which synthesize collagen type IV." (PMID 36936689, 2023). "In 2021, at the latest International Workshops on Alport Syndrome, the term AS spectrum disorder was accepted to refer to all disorders caused by variants in the COL4A3, COL4A4, or COL4A5 genes." (PMID 35880347, 2023). "More than 1000 mutations have been identified in the COL4A3, COL4A4, and COL4A5 genes leading to a reclassification of Alport syndrome and thin basement membrane nephropathy as type IV collagen nephropathies." (PMID 37180518, 2023). "Previous studies have identified that autosomal dominant mutations of Col4A3, Col4A4 or Col4A5 are associated with thin basement membrane nephropathy (TBMN), Alport syndrome and other hereditary kidney diseases." (PMID 37323683, 2023). "Alport syndrome (AS) is a hereditary kidney disease caused by pathogenic variants in COL4A3 and COL4A4 genes with autosomal recessive or autosomal dominant transmission or in the COL4A5 gene with X-linked inheritance." (PMID 36982595, 2023). "Alport syndrome (AS) is a hereditary glomerulonephritis caused by COL4A3, COL4A4 or COL4A5 gene mutations and characterized by abnormalities of glomerular basement membranes (GBMs)." (PMID 37770589, 2023).
Alport syndrome (continued). "Autosomal recessive Alport syndrome (ARAS) is caused by homozygous or compound heterozygous mutations in COL4A3 and COL4A4 genes." (PMID 36982595, 2023). "Treating col4a4 depleted zebrafish larvae (a model of Alport syndrome) with captopril reduced proteinuria in this system." (PMID 35716957, 2022). "Alport syndrome is a hereditary kidney disease caused by mutations in the three genes encoding for collagen IV: COL4A3, COL4A4, and COL4A5." (PMID 36292778, 2022). "One such condition is Alport syndrome, which is caused by variants in COL4A3, COL4A4 or COL4A5 in humans." (PMID 35716957, 2022). "Alport syndrome results from a myriad of variants in the COL4A3, COL4A4, or COL4A5 genes that encode type IV (basement membrane) collagens." (PMID 35223933, 2022). "Mutations in collagen type 4 alpha 3, (COL4A3), collagen type 4 alpha 4 (COL4A4), and collagen type 4 alpha 5 (COL4A5) have been associated with Alport syndrome." (PMID 35309932, 2022). "Alport syndrome is a hereditary disorder characterized by renal impairment, hearing loss, and ocular symptoms and is caused by COL4A3, COL4A4, and COL4A5 mutations." (PMID 36045115, 2022). "Alport syndrome is a genetically heterogenous Type IV collagenopathy linked to the COL4A3, COL4A4, and COL4A5 genes." (PMID 35760791, 2022). "Although a majority of COL4A4 or COL4A3 pathogenic variants have been associated with autosomal recessive Alport syndrome (ARAS), there are also variants associated with autosomal dominant Alport syndrome (ADAS)." (PMID 35842573, 2022). "Pathogenic variants in COL4A5 usually cause X-linked Alport syndrome (XLAS), while alterations in COL4A3 and COL4A4 genes are associated with autosomal dominant AS (ADAS) or autosomal recessive AS (ARAS)." (PMID 35419377, 2022). "Mutations in COL4A3, COL4A4, or COL4A5—encoding the α3, α4, or α5 (IV) chains, respectively—cause various diseases, including thin basement membrane nephropathy (TBMN), Alport syndrome (AS), and late-onset focal segmental glomerulosclerosis (FSGS)." (PMID 36292665, 2022). "Its main cause is heterozygous mutations of COL4A3 or COL4A4, which also cause late-onset focal segmental glomerulosclerosis (FSGS) or autosomal dominant Alport syndrome (ADAS)." (PMID 36292665, 2022). "Individuals with AR Alport syndrome have two pathogenic variants in COL4A3 or COL4A4, and the COL4A3 and COL4A4 genes are affected equally often." (PMID 35602506, 2022). "Currently, three disease-causing genes, namely collagen type IV alpha 3–5 (COL4A3, COL4A4, and COL4A5), have been associated with the occurrence of Alport syndrome." (PMID 36159970, 2022). "Pathogenic variants in COL4A5 usually cause X-linked Alport syndrome (XLAS), whereas those in the COL4A3 or COL4A4 genes are associated with autosomal dominant (AD) or recessive (AR) inheritance." (PMID 35419377, 2022). "Autosomal recessive Alport syndrome (ARAS) is caused by homozygous or compound heterozygous mutations in COL4A3 and COL4A4 genes and accounts for ~5% of patients with AS." (PMID 35547199, 2022). "Many women with X-linked Alport syndrome, and males and females with heterozygous COL4A3 or COL4A4 variants, or sometimes digenic COL4A3 and COL4A4 variants, have only microscopic haematuria." (PMID 33854215, 2021). "Alport syndrome (AS), which is a rare hereditary disease caused by mutations of genes including COL4A3, COL4A4 and COL4A5, has a wide spectrum of phenotypes." (PMID 34774011, 2021). "Alport syndrome (AS) is a rare monogenic hereditary disorder caused by mutations in any of the type IV collagen genes COL4A3, COL4A4 (2q36.3 both) and COL4A5 (Xq22.3)." (PMID 34681722, 2021). "Alport syndrome (AS) is an inherited renal disease caused by variants in COL4A3, COL4A4, or COL4A5 gene." (PMID 34209341, 2021). "High-throughput next-generation sequencing (NGS) technology can improve the diagnosis of Alport syndrome by providing molecular confirmation of COL4A3, COL4A4, or COL4A5 mutations." (PMID 34238373, 2021).
Alport syndrome (continued). "Alport syndrome is a genetic and hereditary disease, caused by mutations in the type IV collagen genes COL4A3, COL4A4 and COL4A5, that affects the glomerular basement membrane of the kidney." (PMID 34681722, 2021). "Alport syndrome is caused by mutations in the genes COL4A3, COL4A4 or COL4A5 and is characterised by progressive glomerular disease, sensorineural hearing loss and ocular defects." (PMID 31044288, 2020). "Their maintenance, regeneration and remodeling have been extensively studied in normal kidney physiology as well as renal diseases, such as X-linked and autosomal recessive Alport syndrome carrying genetic mutations in COL4A3, COL4A4 or COL4A5 gene." (PMID 32210336, 2020). "Alport syndrome is an inherited renal disease caused by mutations in COL4A3, COL4A4, or COL4A5 genes." (PMID 30883042, 2019). "Alport syndrome is caused by mutations in the COL4A3 (OMIM, # 120070), COL4A4 (OMIM, # 120131), or COL4A5 (OMIM, # 303630) genes encoding collagen IVα3, α4, and α5 chains." (PMID 30883042, 2019). "A single mutation in the COL4A4 gene was detected in three male and 10 female patients, a single COL4A3 gene mutation was detected in two male and two female patients, and X-linked Alport syndrome (COL4A5 gene mutation) was detected in four male patients." (PMID 30805210, 2019). "Alport Syndrome (AS) is a clinically and genetically heterogeneous, progressive nephropathy caused by mutations in COL4A3, COL4A4, and COL4A5, which encode type IV collagen (Gubler, 2008; Hudson, Tryggvason, Sundaramoorthy, & Neilson, 2003)." (PMID 30968591, 2019). "In this study, among 417 patients diagnosed or suspected of Alport syndrome in our department during 2014–2017, six were identified with pathogenic variants in COL4A5 plus heterozygous pathogenic variants in COL4A3 or COL4A4, which accounted for 1%." (PMID 30883042, 2019). "Alport syndrome (AS) is a clinically and genetically heterogeneous, progressive nephropathy caused by mutations in COL4A3, COL4A4, and COL4A5, which encode type IV collagen." (PMID 28542346, 2017). "Alport syndrome (AS) is an inherited progressive renal disease caused by mutations in COL4A3, COL4A4, and COL4A5 genes." (PMID 28570636, 2017). "Next-generation sequencing ofCOL4A3, COL4A4, andCOL4A5 before tissue biopsy would be reasonable when suspicion of Alport syndrome is high, e.g. when the patient is a male with hematuria who has an extensive family history of hematuria, deafness, and ESRD." (PMID 28163907, 2017). "Observed versus expected likelihood of Glycine substitutions in the COL4A5, COL4A3 and COL4A4 genes in Alport syndrome and Thin basement membrane nephropathy." (PMID 27627812, 2016). "There are occasional reports of individuals with two COL4A5 mutations, and others with autosomal recessive Alport syndrome and mutations in both COL4A3 and COL4A4 with a later age at onset of renal failure." (PMID 27627812, 2016). "Twelve laboratories involved worldwide in mutation testing for Alport syndrome collaborated to submit 754 novel variants (504 COL4A5, 133 COL4A3, 117 COL4A4 variants) to the LOVD databases." (PMID 27627812, 2016). "Alport syndrome, which contained COL4A4 and COL4A3, was the only enriched term from the OMIM_DISEASE category listed in the chart." (PMID 25109818, 2014). "It was discovered that overexpression of COL4A3 or COL4A4 in the embryonic lens results in microphthalmia and cataract, and mutation in COL4A3, COL4A3, and COL4A5 cause Alport syndrome." (PMID 25124159, 2014). "Alport syndrome is associated with three genes: COL4A5 with the X-linked form (MIM 301050) while COL4A3 and COL4A4 are associated with the autosomal-recessive form (MIM 203780)." (PMID 23398688, 2013). "Autosomal recessive Alport syndrome (ARAS) accounts for about 15% of affected individuals and arises from mutations in both alleles of COL4A3 or COL4A4, which respectively encode the α3(IV) and α4(IV) chains." (PMID 17912554, 2009).
Alport syndrome (continued). "Alport syndrome is a genetic condition characterized by kidney disease, loss of hearing, and eye abnormalities, due to a mutation in the genes encoding alpha-3, alpha-4, and alpha-5 of type IV collagen (COL4A3, COL4A4, COL4A5) or collagen 4 α345 network." (PMID 41299396, 2025). "However, Alport syndrome caused by COL4A3 and COL4A4 changes should always be regarded as potentially serious." (PMID 40806767, 2025). "COL4A3, COL4A4, and COL4A5 are predominantly expressed in and critical for maintaining the structural integrity of the glomerular basement membrane, alterations in these genes lead to basement membrane disruption, which is the primary cause of Alport syndrome." (PMID 40351420, 2025). "Number of variants in COL4A3, COL4A4, and COL4A5 of Alport syndrome." (PMID 40949880, 2025). "Of 91,000 pregnant people screened by a commercial laboratory, the observed carrier frequency for a P/LP variant was one in 279 for COL4A3, one in 332 for COL4A4, and one in 3055 for COL4A5, giving an overall carrier rate of one in 144 for any one of the Alport syndrome genes." (PMID 40317772, 2025). "Alport syndrome (AS), also known as hereditary nephritis, is a genetically and phenotypically heterogeneous disease caused by mutations in genes encoding type IV collagen, specifically the alpha-3, alpha-4, and alpha-5 chains (COL4A3, COL4A4, COL4A5)." (PMID 39981328, 2025). "Collagen IV genes including COLA4A3, COL4A4, and COL4A5, usually associated with hereditary forms of Alport syndrome, represent the emerging most frequent cause of FSGS in patients with otherwise unknown CKD or KF." (PMID 37728640, 2024). "Following a genetic test, the results may indicate a genetic variant in one of the Alport syndrome genes (COL4A3, COL4A4, or COL4A5)." (PMID 38745975, 2024). "Alport syndrome exhibits key clinical features such as hematuria, proteinuria, and a progressive decline in kidney function, attributed to genetic mutations in the COL4A3, COL4A4, and COL4A5 genes." (PMID 38235430, 2023). "This study examined a Romani cohort for pathogenic variants in the COL4A3, COL4A4, and COL4A5 genes that are affected in Alport syndrome (AS), a common cause of genetic kidney disease, characterized by hematuria, proteinuria, end-stage kidney failure, hearing loss, and eye anomalies." (PMID 36844206, 2023). "The diagnosis of Alport syndrome is suspected when an individual has the characteristic clinical features or a family history of Alport syndrome, and it is optimally confirmed by the demonstration of a disease-causing variant in the COL4A5, COL4A3, or COL4A4 genes." (PMID 37895203, 2023). "col4a4 crispants were used as a model of Alport syndrome for these experiments." (PMID 35716957, 2022). "Therefore, depletion of col4a3 or col4a4 in zebrafish is a model of the early stages of Alport syndrome." (PMID 35716957, 2022). "Notably, the COL4A4-knockout mouse has been used to demonstrate that SV function is impaired in the Alport syndrome model." (PMID 35309932, 2022). "Herein, we present a case of Alport syndrome in a 28-year-old woman caused by a novel mutation (Gly1436del) in the COL4A4 gene that was not unveiled until her first pregnancy." (PMID 35028164, 2022). "This COL4A4 variant (c.5007delC) not yet discussed in detail in the literature is associated with Alport syndrome." (PMID 35842573, 2022). "The COL4A3/COL4A4 heterozygous variants were also reported to cause autosomal dominant Alport syndrome (ADAS, OMIM 104200), while homozygous or compound heterozygous variants were responsible for the autosomal recessive Alport syndrome (ARAS)." (PMID 36699462, 2022). "Alport syndrome has been described as a genetic disorder caused by pathogenic mutations in the collagen type IV alpha 3 (COL4A3), collagen type IV alpha 4 (COL4A4), or collagen type IV alpha 5 (COL4A5) genes encoding type IV collagen α3, α4, or α5 chains, respectively." (PMID 35860818, 2022).